SMYD2 (SET and MYND domain containing 2)
Diseases named in the same sentence as SMYD2 in open-access papers (continued):
Sharing a sentence is not in itself a finding about the gene and the disease.
gastric cancer (15 papers, 2017 to 2026). A primary or metastatic malignant neoplasm involving the stomach. "Similarly, SMYD2 is overexpressed in gastric cancer and promotes gastric cancer progression, which is associated with worse clinical outcomes." (PMID 34201935, 2021). "The important role of SMYD2 has been revealed by a growing number of studies in several types of cancer, including breast, liver, and gastric cancers, in addition to leukemia, and ESCC." (PMID 36520265, 2022). "Clinicopathologic associations of SMYD2, known to methylate H3K4 and H3K36, have been reported in gastric cancer and HCC." (PMID 33050946, 2020). "SMYD2 overexpression also contributed to malignant outcome in the development of gastric cancer through the regulation of cell proliferation." (PMID 31548876, 2019). "As an oncogene, SMYD2 is highly expressed in a variety of human tumors such as bladder cancer and gastric cancer, and the high expression of SMYD2 is closely related to the poor prognosis of patients with these diseases." (PMID 31548876, 2019). "SMYD2 is overexpressed in tumor types including esophageal squamous carcinoma, bladder and gastric cancers and pediatric acute lymphoblastic leukemia." (PMID 29856759, 2018). "Consistent with its role in tumorigenesis, knockdown of SMYD2 in esophageal, bladder and gastric cancer models is reported to attenuate proliferation in a variety of tissue culture cells." (PMID 29856759, 2018). "In other tumor types, including esophageal squamous cell carcinoma, gastric carcinoma, acute lymphoblastic leukemia (ALL) and HPV-unrelated head and neck carcinoma, SMYD2 overexpression was associated with disease aggressiveness and worse outcome." (PMID 28187429, 2017). "However, the precise mechanisms by which SMYD2 influences immune infiltration in gastric cancer remain to be fully elucidated." (PMID 40777131, 2025). "NAT10 mediates ac4C acetylation of SMYD2 to promote progression of gastric cancer." (PMID 39640362, 2024). "In addition, SMYD2 can promote the proliferation, migration and invasion of gastric cancer, esophageal squamous cell carcinoma, head and neck tumor cells, and other malignant biological functions." (PMID 35432530, 2022). "SMYD2 protein expression levels were determined by immunohistochemistry in a cohort of 147 primary gastric cancer samples and its overexpression significantly correlated with features that influence patient survival, such as lymph node metastasis, larger tumor size and depth of tumor invasion." (PMID 33050946, 2020). "In addition, SMYD2 is also overexpressed in gastric cancer, pancreatic ductal adenocarcinoma (PDAC), papillary thyroid carcinoma, hepatocellular carcinoma, and colon cancer." (PMID 31370883, 2019). "NETosis promote gastric cancer metastasis by increasing NAT10‐mediated N4‐acetylcytidine modification of SMYD2 mRNA, which stabilises SMYD2 and enhances cancer cell invasion and migration." (PMID 41503514, 2026). "The interaction between gastric cancer cells and NETs, which boosts cell viability, migration, and invasion, is influenced by NAT10 and Set and MYND domain containing 2(SMYD2)." (PMID 39791162, 2025). "SMYD2 has been shown to act as an oncogene in many cancers, including esophageal squamous cell carcinoma (ESCC), bladder cancer, gastric cancer, triple-negative breast cancer, and hepatocellular carcinoma 16-19." (PMID 31754403, 2019). "In addition, overexpression of SMYD2 has been observed in hepatocellular carcinoma (HCC), gastric cancer, pancreatic ductal adenocarcinoma (PDAC), papillary thyroid carcinoma, and colon cancer." (PMID 36520265, 2022). "This study highlights the negative prognostic impact of SMYD2 in gastric cancer." (PMID 33050946, 2020). "SMYD2 has also been found to have a negative impact on gastric cancer survival." (PMID 33050946, 2020).
esophageal squamous cell carcinoma (13 papers, 2015 to 2024). Esophageal squamous cell carcinoma (ESCC) is a type of esophageal carcinoma (EC) that can affect any part of the esophagus, but is usually located in the upper or middle third. "Increased SMYD2 expression has been significantly associated with the low survival rate of patients with esophageal squamous cell carcinoma, revealing the carcinogenic potential of SMYD2." (PMID 34335697, 2021). "SMYD2 has been reported to be overexpressed in esophageal squamous cell carcinoma (ESCC) primary tumor samples and in pediatric acute lymphoblastic leukemia correlated with a poor prognosis and patient survival." (PMID 29487338, 2018). "Knockdown of SMYD2 in esophageal squamous cell carcinoma inhibited tumor cell growth; with overexpression of SMYD2, promoted proliferation." (PMID 27790639, 2016). "SMYD2 is overexpressed in leukemia and esophageal squamous cell carcinoma." (PMID 27790639, 2016). "Several studies reported that SMYD2 is overexpressed in the tumor cells lines and patients’ tissues of some cancer types, including esophageal squamous cell carcinoma and acute lymphoblastic leukemia, which suggests SMYD2 as a potential drug target in these cancers." (PMID 25562686, 2015). "This study identified 1032 Kme1 sites and quantified 273 of them in esophageal squamous cell carcinoma (ESCC) and identified 1861 Kme1 sites and quantified 664 of them in SMYD2-overexpressed ESCC." (PMID 38862432, 2024). "Overexpression of SMYD2 has been reported in primary tumor samples of esophageal squamous cell carcinoma (ESCC) and pediatric acute lymphoblastic leukemia (ALL); the expression level is correlated with a poor prognosis and shortened survival of the patients." (PMID 36520265, 2022). "In esophageal squamous cell carcinoma (ESCC), overexpression of SMYD2 protein is observed in most primary tumor samples (76.5%) and in some ESCC cell lines (25.6%)." (PMID 31370883, 2019). "Over-expression of SMYD2 and NSD2 was also noticed in various cancers, for instance, esophageal squamous cell carcinoma, pediatric lymphoblastic leukemia, colon and skin cancers." (PMID 31160694, 2019).
lung carcinoma (12 papers, 2019 to 2024). "Therefore, the mechanism underlying SMYD2-mediated RPS7-driven lung cancer growth will need to be further explored in subsequent studies." (PMID 33935284, 2021). "For example, lung cancer metastasis was facilitated by SMYD2-regulated SMAD3 expression in response to TGF-β, while colorectal cancer EMT was inhibited by miR-140 by directly downregulating SMAD3 and deactivating the TGF-β signaling pathway." (PMID 38641828, 2024). "Recently, we reported that SMYD2 knockdown reduced lung cancer metastasis in vitro and in vivo metastasis analyses, but similar to SMYD5 knockdown, SMYD2 knockdown did not affect cell growth inhibition in lung cancer cell lines." (PMID 38723947, 2024). "We further tested the role of loaded NPs in a urethane-induced lung cancer mouse model (n = 40 mice in three independent trials, 20 mice in control group) to check the role of SMYD2 at various time points of lung cancer development." (PMID 37513898, 2023). "SMYD2 shows promise as a novel target for various carcinomas, particularly in lung cancer, where it contributes to cancer cell proliferation." (PMID 37513898, 2023). "In particular, an in vitro EMT system was used to generate highly invasive lung cancer cell lines, and the results showed that SMYD2 knockdown clearly suppressed migration and invasion." (PMID 37121971, 2023). "In lung cancer, downregulation of SMYD2 induces suppression of cell growth in cisplatin-resistant lung cancer cells." (PMID 37121971, 2023). "The novelty of this study lies in treating urethane-induced lung carcinoma using LLY-507-loaded iron oxide nanoparticles to investigate SMYD2’s role in NSCLC treatment." (PMID 37513898, 2023). "Downregulation of SMYD2 suppressed the migration and invasion of lung cancer cell lines by reducing SMAD3 expression through SMYD2-mediated epigenetic regulation." (PMID 37121971, 2023). "Although many reports have suggested that SMYD2 is related to cancer progression, metastasis regulation by SMYD2, especially in lung cancer, is not fully understood." (PMID 37121971, 2023). "To verify the function of SMYD2 in lung cancer, we constructed shSMYD2 and shCont H1299 cell lines under puromycin selection." (PMID 37121971, 2023). "Based on the GO terms, we first designed SMYD2-specific siRNA (siSMYD2) and control siRNA (siCont) and transfected them into two lung cancer cell lines (H1299 and H1703)." (PMID 37121971, 2023). "We validated the downregulation of SMAD3 by SMYD2 knockdown in lung cancer cell lines by qRT–PCR analysis." (PMID 37121971, 2023). "SMYD2 has a higher expression in multiple malignancies, including lung cancer, and is responsible for the worst outcomes and poor prognosis." (PMID 37513898, 2023). "Experiments with cultured lung cancer cells demonstrated that SMYD2 plays a role in epithelial-mesenchymal transition, a cellular transformation process that leads to metastatic growth." (PMID 37121971, 2023). "The novelty of this work is the reduction in tumor growth in mouse lungs by inhibiting SMYD2 by using LLY-507-loaded iron oxide nanoparticles in the urethane-induced lung cancer mouse model." (PMID 37513898, 2023). "In conclusion, using the TCGA portal, we observed clear overexpression of SMYD2 in lung cancer tissues compared to normal tissues." (PMID 37121971, 2023). "To assess SMYD2 expression in lung cancer, we analyzed the RNA-seq results in normal lung (n = 51) and lung cancer (n = 502) samples derived from The Cancer Genome Atlas (TCGA) portal and found that SMYD2 was overexpressed at the transcriptional level." (PMID 37121971, 2023).
lung carcinoma (continued). "Next, to assess the function of SMYD2, we performed RNA-seq analysis after transfection of lung cancer cell lines (H1703 and H1299) with siSMYD2 and siCont." (PMID 37121971, 2023). "A subcutaneous transplanted tumor model was used to evaluate the effects of SMYD2 and Baicalein on the proliferation of lung cancer." (PMID 35432530, 2022). "Previous data also demonstrated that SMYD2-mediated ALK methylation dramatically promoted lung cancer development, and SMYD2 was also involved the growth of MLL-AF9 induced leukemogenesis." (PMID 31548876, 2019). "Additionally, treatment with baicalein, which is a flavonoid from Scutellaria baicalensis, inhibits SMYD2 expression, suppressing lung cancer growth, migration, and invasion." (PMID 39482529, 2024). "Furthermore, SMYD2 regulates lung cancer metastasis by directly controlling SMAD family member 3 (SMAD3), which regulates the progression of lung cancer." (PMID 39482529, 2024). "Moreover, in the patient cohort analysis, patients with high SMYD2 expression had a poor prognosis in terms of recurrence- and metastasis-free survival, implying that SMYD2 function is strongly related to lung cancer proliferation and metastasis." (PMID 37121971, 2023). "Additionally, immunohistochemical analysis of lung cancer and normal lung tissues showed that SMYD2 expression was increased in lung cancer tissues (adenocarcinoma and squamous cell carcinoma) compared to normal tissues." (PMID 37121971, 2023). "Taken together, these findings present SMYD2 as a regulator of lung cancer metastasis." (PMID 37121971, 2023). "Thus, in this study, to verify the function of SMYD2 in highly invasive lung cancer, we generated invasive H1299 cell lines using a Transwell system." (PMID 37121971, 2023). "Thus, SMYD2 is a potential anti-metastasis target for lung cancer treatment, suggesting that the incidence of micro/macrometastasis in lung cancer will be reduced by SMYD2-specific inhibitors." (PMID 37121971, 2023). "Furthermore, in two in vivo metastasis studies, downregulation of SMYD2 inhibited the metastasis of lung cancer cell lines, implying that SMYD2 is a potential regulator of lung cancer metastasis." (PMID 37121971, 2023). "Thus, we suggest that SMYD2 downregulation inhibits the metastasis of invasive lung cancer and primary lung cancer." (PMID 37121971, 2023). "Thus, we suggest that downregulation of SMAD3 by SMYD2 knockdown strongly affects the migration and invasion of lung cancer cell lines." (PMID 37121971, 2023). "As an example, the binding of a small molecule to the proline-rich sequences of MYND may be possible in cells where the tumor suppressor EBP41L3 links to SMYD2, as is the case in meningiomas, a brain cancer, and lung cancer." (PMID 36838987, 2023). "Thus, we suggest that SMYD2 downregulation effectively suppresses cancer metastasis and that SMYD2 is a potential metastasis regulator for lung cancer." (PMID 37121971, 2023). "This study investigated whether the inhibitory effect of Baicalein on lung cancer cells was related to the SMYD2/RPS7 signaling pathway." (PMID 35432530, 2022). "Meanwhile, the role of SMYD2/RPS7 signaling pathway in lung cancer was analyzed." (PMID 35432530, 2022). "It was found that Baicalein could inhibit the proliferation, invasion, and metastasis of lung cancer cells by inhibiting the expression of SMYD2 in A549 cells." (PMID 35432530, 2022). "In this study, SMYD2 expression was upregulated in lung cancer patients." (PMID 35432530, 2022). "Furthermore, we explored the role of SMYD2 in cell proliferation, migration, and invasion of lung cancer cells both in vitro and in xenograft mouse models, and investigated the molecular mechanisms underlying its role." (PMID 33935284, 2021). "SMYD2 overexpression in lung cancer tissues and cell lines may influence the expression of a variety of genes." (PMID 33935284, 2021).
lung carcinoma (continued). "However, amazing results were seen in the LLY-507-loaded IONP group (average weight = 37 g), as there was no inflammation or congestion in that group, meaning that the SMYD2 inhibitor LLY-507 has an anti-inflammatory effect in the urethane-induced lung cancer model." (PMID 37513898, 2023). "Moreover, in the TCGA data, we found upregulation of SMAD3 in lung cancer samples compared to normal samples, as shown by SMYD2 upregulation, suggesting that SMAD3 regulation by SMYD2 could regulate lung cancer metastasis." (PMID 37121971, 2023). "Thus, in this study, we hypothesized that SMYD2 was overexpressed in lung cancer and identified SMAD3 as a direct target of SMYD2 via epigenetic regulation that promotes lung cancer metastasis." (PMID 37121971, 2023). "Thus, we suggest that SMYD2 is a potential metastasis regulator and that the development of SMYD2-specific inhibitors may help to increase the efficacy of lung cancer treatment." (PMID 37121971, 2023). "Together, these data suggest that SMYD2 may be a regulator of lung cancer metastasis." (PMID 37121971, 2023). "Thus, inhibition of SMYD2 with a specific inhibitor suppressed lung cancer metastasis, and these results suggest that the development of an SMYD2-specific inhibitor might be important for lung cancer treatment." (PMID 37121971, 2023). "Here, we found that the histone methyltransferase SMYD2 is overexpressed in lung cancer and that knockdown of SMYD2 could reduce the rates of cell migration and invasion in lung cancer cell lines via direct downregulation of SMAD3 via SMYD2-mediated epigenetic regulation." (PMID 37121971, 2023). "Additionally, the in vivo model confirmed that SMYD2 is related to lung cancer metastasis." (PMID 37121971, 2023). "Thus, on the basis of the GO term and cohort analysis results, we suggest that SMYD2 may be involved in lung cancer progression, especially metastasis." (PMID 37121971, 2023). "In addition, animal experiments showed that SMYD2 knockdown inhibited lung cancer tumor growth." (PMID 35432530, 2022). "However, the role of SMYD2 in lung cancer remains to be further studied." (PMID 35432530, 2022). "In addition, SMYD2 was highly expressed in lung cancer cells A549 and NCI-H1299." (PMID 35432530, 2022). "Moreover, SMYD2 promotes the growth of lung cancer via mediating ALK methylation." (PMID 33935284, 2021). "In our study, we tested the effects of SMYD2 inhibition on TMPRSS2 expression in HT-29 cells and Caco-2 cells, two human colorectal adenocarcinoma cell lines, and Calu-3 cells, one lung cancer cell line." (PMID 35455942, 2022). "Therefore, our results suggest that SMYD family members (specifically SMYD2 and SMYD5) are important factors in lung cancer metastasis." (PMID 38723947, 2024). "Interestingly, the expression of SMYD2 and SMAD3 was increased in In-H1299 cells, suggesting that SMYD2 may be related to the metastatic signature of invasive lung cancer." (PMID 37121971, 2023).
hepatocellular carcinoma (11 papers, 2015 to 2026). A malignant tumor that arises from hepatocytes. "In addition, one study found that positive expression of SMYD2 was associated with poor prognosis in patients with hepatocellular carcinoma." (PMID 33459509, 2021). "In hepatocellular carcinoma, SMYD2 overexpression increases proliferation by directly binding to c-Myc and increasing its protein stability." (PMID 39482529, 2024). "In the current study, we showed SMYD2 is overexpressed in hepatocellular carcinoma and correlates with unfavorable clinical outcomes." (PMID 36611819, 2022). "Taken together, in the current study, we demonstrated that SMYD2 participates in the progression of hepatocellular carcinoma and correlates with poor clinical outcomes." (PMID 36611819, 2022). "To investigate the function of SMYD2 in hepatocellular carcinoma, we detected the SMYD2 expression level in 80 pairs of HCC tissues and their paired normal specimens using RT-qPCR." (PMID 36611819, 2022). "In addition, we confirmed the interaction between endogenous SMYD2 and β-catenin by co-immunoprecipitation assays in two cancer cell lines, HCT116 (colon cancer) and SNU475 (hepatocellular carcinoma (HCC))." (PMID 28915556, 2017).
renal cell carcinoma (10 papers, 2016 to 2025). "In contrast, low SMYD2 expression is associated with low survival in patients with renal cell carcinoma (RCC) associated with complex karyotype acquisition and cancer progression." (PMID 34201935, 2021). "The SMYD2 gene resides in 1q32–q41, a chromosomal region mostly amplified in esophageal and renal cell carcinoma, gastric, colon, pancreatic, lung, bladder, TNBC, and PC." (PMID 35884603, 2022). "Mechanistically, inhibition of SMYD2 suppressed the progression of renal cell carcinoma by downregulating microRNA-125b." (PMID 34544413, 2021). "In line with our findings in AML, low levels of SMYD2 correlated with shorter survival in patients with renal cell carcinoma and acquisition of complex karyotype and disease progression in chronic lymphocytic leukemia." (PMID 28187429, 2017). "However, further investigation is warranted to provide a comprehensive understanding of the involvement of SMYD2 in renal cell carcinoma." (PMID 39440063, 2024).